SRGAP2D (SLIT-ROBO Rho GTPase activating protein 2D (pseudogene))
Gene: Transcribed unprocessed pseudogene on chromosome 1 (143,975,087 to 144,068,350, forward strand). Ensembl gene ENSG00000270872.
Diseases named in the same sentence as SRGAP2D in open-access papers:
SRGAP2D is named in the same sentence as 2 diseases in open-access papers, as found by Europe PMC text mining. Sharing a sentence is not in itself a finding about the gene and the disease. The quoted sentences say what the papers report.
breast carcinoma (1 paper, 2015). "For some of the loci, such as STXBP4, SRGAP2D and RAD51L1, the breast cancer association is highly significant and thus the number of likely SNPs is relatively small." (PMID 26472073, 2015).
SRGAP2D also shares sentences with these, for which no sentence is quoted: cancer (1 paper).